TNF (tumor necrosis factor)
Diseases named in the same sentence as TNF in open-access papers (continued):
Sharing a sentence is not in itself a finding about the gene and the disease.
cytomegalovirus infection (continued). "The lack of impact of HCMV infection on measles-specific innate pro-inflammatory cytokines IL-1β and TNF, the Th1 cytokine IFN-γ, the Th2 cytokine IL-4 and the anti-inflammatory cytokine IL-10 is encouraging." (PMID 32582177, 2020). "Since the ligands for TNF-α (TNFR1 and TNFR2), have both been shown to be modulated by HCMV infection, we first examined whether RNA1.2 influences surface expression of these receptors." (PMID 32793512, 2020). "Thus, myeloid cells (primary targets for CMV infection) are the producers, amplifiers, as well as responders to TNF, while non-myeloid cells function primarily as responders in this signaling cascade." (PMID 33126536, 2020). "HCMV infection may upregulate the expression of TLR2 and TNF-α." (PMID 25435993, 2015). "We found that IL-6 and TNF-α levels in the cells infected with HCMV were significantly higher than in the mock infected cells, but curcumin significantly reduced the secretion of the two cytokines, suggesting that curcumin may be an effective anti-HCMV infection agent." (PMID 25088288, 2014). "Interestingly, non-TNFα treated HK2 KO and HIF1A KO cells showed an increase in HCMV plaque formation relative to the vehicle pretreated control ntg cells, suggesting that HIF1A and HK2 may play a role in restricting HCMV infection that is independent of TNFα signaling." (PMID 35834576, 2022). "Herein, we show that in the non-sex-stratified analysis, HCMV infection had little impact on in vitro innate cytokine responses to a panel consisting of TLR2, 4, 5 and 7/8 ligands, except for reduced TNF-α reactivity to TLR2 stimulation with HKLM." (PMID 32707906, 2020). "When males and females were analysed separately in our study, we found that HCMV+ females had reduced TNF-α and TNF-α:IL-10 to HKLM stimulation, but there was no such effect of HCMV infection in males." (PMID 32707906, 2020).
endometritis (77 papers, 2012 to 2025). An acute or chronic, usually bacterial infectious process affecting the endometrium. "For instance, IL1β is significantly upregulated in PBIE in susceptible mares, while IL6 or TNFα are predominant in chronic subclinical endometritis and overexpression of IL1β, IL6, and TNFα is observed in subacute suppurative endometritis." (PMID 37869492, 2023). "Meanwhile, endometritis caused by bacterial infection usually involves inflammatory factors such as IL-1β, IL-6, and TNF-α." (PMID 36846263, 2023). "Numerous studies have demonstrated that LPS stimulates the production of IL-6, IL-1β, and TNF-α, which are also implicated in the pathogenesis of endometritis." (PMID 37570258, 2023). "Previous studies by Fumuso and co-workers showed that mares susceptible to persistent endometritis had significant upregulated cellular immune response (IL-1β, IL-6, TNF-α and IL-8) and down-regulated anti-inflammatory activity (IL-10) compared to resistant mares at estrous baseline levels." (PMID 22458733, 2012). "In summary, the present study provided strong evidence of the protective effects of TREM‐1 deficiency against LPS‐induced endometritis in mice, the mechanism of which could be deduced as knocking out of the Trem‐1 inhibited the LPS‐induced production of IL‐1β, IL‐6 and TNF‐α." (PMID 31365951, 2019). "Numerous inflammatory mediators, including tumor necrosis factor α (TNF-α), and interleukin (IL)-1β, IL-6, and IL-8, are released during endometritis, and inhibition of these inflammatory factors can effectively reduce the severity of bacterial endometritis." (PMID 40431224, 2025). "Studies have found that Escherichia coli increases inflammatory factors, such as iNOS, IL-1β, TNF-α, IL-6, etc., through the NF-κB signaling pathway, leading to endometritis." (PMID 40514455, 2025). "The ABX+DI+Guanosine+E. coli group reduced endometritis inflammatory markers, including IL‐1β and TNF‐α concentrations and expression level, compared with the ABX+DI+E. coli group." (PMID 40227949, 2025). "Berberine and carvacrol, respectively, were found to significantly reduce the expression of TNF-a, IL-1β, IL-6, and IL-8 after treatment of endometritis in mice, and the differences were significant compared with those in the model group (p < 0.01)." (PMID 40431224, 2025). "In the horse, TNFα and its receptors were shown to be expressed in the endometrial stromal and epithelial cells, with elevated TNFα expression reported in mares with endometritis and chronic endometrial fibrosis." (PMID 41373504, 2025). "✧Pro-inflammatory activator (NF-κB, IL-1 β, TNF-α) levels were suppressed.✧Oxidative stress was alleviated via the upregulation of Nrf-2.✧Relieved endometritis by activating the NF-κB/Nrf2 signaling pathway." (PMID 39408650, 2024). "Their research also highlighted the role of the ECS components in modulating inflammatory responses, with elevated levels of pro-inflammatory cytokines such as TNF and IL1B associated with endometritis." (PMID 39273135, 2024). "Concerning the APPs and cytokines, the serum levels of Hp, SAA, Cp, IL-6, IL-10 and TNF-α were significantly (P˂0.05) increased in buffalo–cows with endometritis compared to healthy ones." (PMID 38459095, 2024). "The results revealed a significant increase in the expression levels of inflammatory-related factors TNF-α (p < 0.001), IL-8 (p < 0.001), and IL-10 (p < 0.001) in the uterus with endometritis." (PMID 38473153, 2024). "The results showed that S. aureus significantly increased the levels of MPO, TNF‐α, IL‐1β and IL‐6 in uterine tissue, and increased the expression of p‐p65 and p‐IκBα proteins in uterine tissue to induce endometritis in mice (p < 0.05)." (PMID 39042561, 2024). "The results showed that the IL-6, IL-1β, and TNF-α were decreased, and the IL-10 was increased in mice with endometritis treated with naringin." (PMID 39234103, 2024).
endometritis (continued). "TNF‐α, IL‐1 and IL‐6 are the main pro‐inflammatory cytokines, and their levels reflect the severity of endometritis." (PMID 39042561, 2024). "Increased inflammatory cytokines TNF-α, IL-6, and IL-1β were observed in patients with endometritis." (PMID 38169293, 2024). "The research in this study demonstrated that the transvaginal instillation of a specific amount of LPS induced acute endometritis in mice, leading to increased levels of pro-inflammatory cytokines such as TNF-α, IL-6, and IL-1β." (PMID 39062636, 2024). "In LPS-induced endometritis in mice, alpinetin exerts its anti-inflammatory effects by inhibiting the expression of IL-6, IL-1β, and TNF-α." (PMID 37570258, 2023). "For instance, one study finds that miR‐34a induces the release of the proinflammatory cytokines including IL‐1β, IL‐6, and TNF‐α in endometritis." (PMID 34861059, 2022). "First, we tested the effects of heat-killed C. butyricum and spent culture supernatants (SCS) from C. butyricum on TNF-α and IL-1β expression in E. coli-induced endometritis." (PMID 36321897, 2022). "Matrine reduced the expression of TNF-α and IL-1β and attenuated the uterus injury in the lipoteichoic acid-induced mouse endometritis model." (PMID 36249421, 2022). "IFNτ acts as an anti-inflammatory agent by suppressing the NFkβ mechanism and inhibits production of IL1B and TNFα in the endometritis in mice." (PMID 36428366, 2022). "The results showed that C. butyricum decreased E. coli-induced endometritis by downregulating the proinflammatory cytokines TNF-α and IL-1β to directly inhibit the inflammatory response." (PMID 36321897, 2022). "Mice were injected with different concentrations of Escherichia coli (E. coli) for 24 h to establish a model of endometritis, and we detected the mRNA and protein expressions of IL-6, IL-1β and TNF-α in the mouse uterine tissues." (PMID 35744807, 2022). "Consistent with results from previous studies, TNF-α and IL-1β concentrations were markedly elevated in the E. coli-induced endometritis group in this study." (PMID 36321897, 2022). "Meanwhile, previous studies have shown that TNF-α, IL-6, and IL-1β were upregulated in S. aureus-induced endometritis." (PMID 35937303, 2022). "In this study, we successfully established an endometritis model in mouse using Escherichia coli; endometrial integrity was destroyed, inflammatory cells infiltrated and the expression of IL-6, IL-1β, TNF-α was significantly up-regulated." (PMID 35744807, 2022). "qRT-PCR results showed that the endometritis tissues secreted the proinflammatory cytokines IL-1β, IL-6, and TNF-α, but there was a decreased secretion of IL-10, an anti-inflammatory mediator." (PMID 34504639, 2021). "In this experiment, bAD-MSCs were co-cultured within a bovine endometrial epithelial cell inflammation model; we found that the levels of IL-1β, TNF-α, and IL-6 were significantly lower than those in the endometritis model group." (PMID 34746277, 2021). "The results showed that LPS treatment for 12 h significantly increased the levels of IL-6, IL-1β, and TNF‐α, indicating the successful establishment of the LPS-induced endometritis model in mice." (PMID 34976866, 2021). "The results of qPCR assay showed that the secretion of pro‐inflammatory cytokines IL‐1β and TNF‐α was markedly increased in the uterine tissues from mice with endometritis." (PMID 31756048, 2020). "Conversely, upstream regulators including TNF, LPS, interferon, IL‐1β, and IL‐6 were activated in oocytes of bacteria‐infused heifers at Day 60 long after the resolution of uterine infection." (PMID 32821881, 2020). "In contrast, elevated serum and tissue concentrations of pro-inflammatory cytokines, including TNF-α, IL-1β, and IL-6, were observed in cows with metritis, endometritis, or subclinical endometritis." (PMID 33132596, 2020).
endometritis (continued). "Second, we focused on the protective effects of AS IV against LPS-induced endometritis concerning the aspects of histopathological changes, inflammatory cytokine levels (IL-1β and TNF-α), concentration of NO, and myeloperoxidase activity in the uterus." (PMID 30669661, 2019). "In agreement with our results, IL-1, IL-6, IL-10, and TNF have been found to be significantly downregulated in a mare endometritis model with chronic pathological endometrial changes, including fibrosis, after mesenchymal stem cell treatment." (PMID 29954457, 2018). "Supporting current results, researchers found significant increase in IL-1, IL-6, IL-10, and TNF in a mare model of endometritis with chronic pathological endometrial changes including fibrosis." (PMID 28883083, 2017). "The expression of the pro-inflammatory mediators IL-1β and TNF-α were detected using a qPCR assay of the LPS-induced endometritis treatment." (PMID 28223539, 2017). "The listed uterine washing tests have shown only slight changes in the concentration of TNF-α, IL-6 and IL-10 in cows with subclinical endometritis." (PMID 25846950, 2015). "Serum concentrations of TNF-α were higher in cows with metritis, clinical endometritis or subclinical endometritis compared to normal cows (P < 0.05)." (PMID 24209779, 2013). "In this study, postpartum dairy cows diagnosed with metritis, clinical endometritis, or subclinical endometritis had higher serum concentrations of adiponectin, TNF-α, IL-1β and IL-6 compared to normal cows." (PMID 24209779, 2013). "Cows with metritis or clinical endometritis had higher serum concentrations of adiponectin, leptin, TNF-alpha, IL-1beta and IL-6 compared to normal cows (P < 0.05)." (PMID 24209779, 2013). "Additionally, KEGG enrichment analysis indicates that the therapeutic effect of the TCMF on endometritis is primarily attributed to the TNF signaling pathway." (PMID 41002185, 2025). "KEGG analysis suggests that the therapeutic mechanisms of the TCMF in treating endometritis may involve the TNF signaling pathway, IL-17 signaling pathway, and FoxO signaling pathway." (PMID 41002185, 2025). "In vivo, it alleviated LPS-induced endometritis in mice and reduced TNF-α and IL-1β levels." (PMID 40430456, 2025). "It is possible that TNF-α, IL-1β, IL-4 and IL-10 significantly generated during endometritis, by increasing the viability of stromal cells, may affect the regeneration of endometrial cells damaged by inflammation." (PMID 39843578, 2025). "However, pretreatment of luteolin significantly attenuated TNF-α, IL-6, and IL-1β production in S. aureus–induced endometritis mice." (PMID 38169293, 2024). "The contents of TNF‐α and IL‐1β were detected by ELISA in S. aureus‐induced endometritis model." (PMID 39462269, 2024). "In addition, our study also verified the effects of inflammatory cytokines (IL-1β, IL-6, and TNF-α) in the endometritis model." (PMID 36846263, 2023). "TNF-α and IL-1β content increases in inflamed tissues, including endometritis." (PMID 36230459, 2022). "Cl-amidine may inhibit the synthesis of pro-inflammatory cytokines (IL-, IL-6, and TNF-) in LPS-induced endometritis, implying that it has therapeutic potential in the prevention of NETs and the treatment of chronic endometritis." (PMID 35565576, 2022). "Pro-inflammatory cytokines such as TNF-α and IL-1β have been found in endometritis." (PMID 36321897, 2022). "Additionally, up-regulation of miR-92b improved the outcome of endometritis, as indicated by the mitigated pathological conditions, as well as the down-regulation of IL-6 and TNF-α secretion." (PMID 33867846, 2021). "Overexpression of miR-19a reduced TNF-α in a model of LPS-induced endometritis." (PMID 33182773, 2020). "In addition, cows with metritis or clinical endometritis show higher serum concentrations of leptin, adiponectin, IL-1β, IL-6and TNF-α." (PMID 31311492, 2019). "It has been reported that suppressing the expression of IL-1β and TNF-α could attenuate LPS-induced endometritis." (PMID 30669661, 2019).
endometritis (continued). "In the present study, AS IV inhibited LPS-induced production of IL-1β and TNF-α, meaning that AS IV could attenuate LPS-induced endometritis by inhibiting these inflammatory cytokines." (PMID 30669661, 2019). "They suggested that IL-1β, IL-8, and TNF-α might represent potential marker genes for the detection of cows with subclinical endometritis and for monitoring new therapeutic approaches." (PMID 27051191, 2016). "At the same time, a high level of TNF-α was detected in cows with subclinical endometritis." (PMID 25846950, 2015). "Concentrations of TNF-α were reduced during Week 7 in cows with metritis or clinical endometritis." (PMID 24209779, 2013). "Furthermore, serum leptin, TNF-alpha, IL-1beta and IL-6 were higher in cows with subclinical endometritis compared to normal cows (P < 0.05), and insulin and IGF-1 concentrations were lower in cows with metritis or clinical endometritis." (PMID 24209779, 2013). "In the present study, serum TNF-α concentrations were higher in subclinical cows compared to normal cows, and higher in cows with metritis or clinical endometritis cows compared to those with subclinical endometritis or normal cows." (PMID 24209779, 2013). "An increase in the relative mRNA abundance of pro-inflammatory cytokines (IL-1β, IL-8, IL-6, and TNF-α) has also been detected in the cervical mucus of buffalo along with low intra-follicular estradiol levels, which suggests that endometritis could impede the follicular steroidogenesis." (PMID 39858163, 2025). "Hence, we concluded that ICA might express its protective effect by attenuation of the production of IL-1β, IL-6, and TNF-α as well as boosting the production of IL-10 in LPS-induced endometritis." (PMID 36142129, 2022). "The serum CRP levels increased by about 6 folds in SCE buffaloes than control that could be attributed to the promotion of mononuclear cells in response to uterine infection to produce their cytokines TNF-α and IL-8 which subsequently stimulated the emission of CRP from liver into blood stream." (PMID 32368278, 2020). "Endometritis is characterized by the high expression of CD14, TLR4, IL-1α, IL1-β, IL-6, IL-8, and TNF-α in uterine tissue and cervical mucus." (PMID 39858163, 2025). "This study investigates postpartum bovine uterine tissues, comparing inflammatory cytokines (IL-1β, IL-6, TNF-α) and oxidative-stress-related factors (GPx, SOD, CAT) between healthy and endometritis groups." (PMID 40646747, 2025). "✧Relieved the endometritis in BEECs by enhancing the antioxidant response (Nrf2, HO-1, and NGO1) and the downregulation of pro-inflammatory cytokines (TNF-α and IL-6)." (PMID 39408650, 2024). "Compared to resistant cows, endometritis-affected cows produced considerably more of the genes TLR4, LITAF, TNF-α, TKT, RPIA, TLR7, TNF-α, TKT, and AMPD1." (PMID 39195794, 2024). "✧Prevented the endometritis via inhibition of MPO, NF-Κb, TNF-α, and IL-1β.✧Enhanced the expressions of Nrf2 and HO-1 levels and suppressed the MDA content." (PMID 39408650, 2024). "The inflammatory response to intrauterine adhesions can increase IL-6 and TNF-α in menstrual effluent in the uterus, and GYS treatment significantly reduced expression of the pro-inflammatory cytokines in rats with endometritis." (PMID 38630770, 2024). "On the other hand, it was reported that the peroxisome proliferator-activated receptor γ (PPARγ) inhibits pro-inflammatory cytokines (TNFα, IL-1β, and IL-6), TLR4, and NF-κB, relieving LPS-induced endometritis in pig endometrial epithelial cells (EECs)." (PMID 39408650, 2024). "The serum levels of Hp, SAA, Cp, IL-6, IL-10, TNF-α, NO and MDA were significantly (P˂0.05) increased, along with reduction of CAT, GPx, SOD and TAC in buffalo–cows with endometritis compared to healthy ones." (PMID 38459095, 2024).